ALB (albumin)
Diseases named in the same sentence as ALB in open-access papers (continued):
Sharing a sentence is not in itself a finding about the gene and the disease.
infection (continued). "Infection of mice with S. mansoni showed a significant increase in serum levels of ALT (P < 0.01, P < 0.001) with a significant decrease in both albumin (P < 0.01) 18 weeks PI, and hepatic GSH (P < 0.001) 10 and 18 weeks PI in comparison with the uninfected untreated group." (PMID 22236605, 2012). "In infected non-vaccinated control-2, albumin value was 31.19 and globulin value 68.81 on 21st day post infection." (PMID 23109947, 2012). "Upon infection the fish needed to dramatically increase production of the APR proteins and appear to sacrifice the transcription of normal plasma proteins as seen for serum albumin, globins and apoliproteins." (PMID 20602791, 2010). "At 3, 4, 6, 8 and 12 hours post-infection (hpi), cells were fixed with 4% Paraformaldehyde, permeabilized with Phosphate Buffered Saline (PBS) 0.5% Triton X-100 and incubated for one hour in PBS 0.1% Triton X-100 and 2% Bovine Serum Albumin." (PMID 20236536, 2010). "In the current study, serum ALT, total bilirubin and albumin levels were not significantly elevated in children with ongoing infection in comparison to controls." (PMID 20015406, 2009). "Routine albumin is not recommended in patients with other sources of infection." (PMID 41270866, 2025). "In addition, owing to the relatively long half-life of serum albumin, its levels do not exhibit a clear correlation with the body’s condition before infection or the acute inflammatory response." (PMID 40313464, 2025). "However, albumin concentrations are also affected by processes such as inflammation and infection, so there is no consensus on optimal limits and reference ranges for serum values to assess nutritional status in older adults." (PMID 40969368, 2025). "Importantly, albumin is classified as a negative acute-phase reactant, and its levels decline in response to systemic inflammation, infection, or surgical stress." (PMID 40698225, 2025). "In addition, albumin infusion did not lead to a reduction in fluid requirements, infection rate, or mortality in the ICU." (PMID 40649163, 2025). "Higher serum albumin (p < 0.01), lower serum hsCRP (p < 0.01), lower risk of mortality, and shorter LoHS (p < 0.01).No significant impact on APACHE II scores, incidence of infection-related complications, or surgical interventions." (PMID 40805976, 2025). "Ascites, HE, creatinine, sodium, bilirubin, albumin, and age are well-known survival predictors that were included in the established predictive models but in our study we wanted to highlight the significance of often overlooked variables like SIRS, fibrinogen, and infections." (PMID 39594174, 2024). "Furthermore, ALB, a negative acute-phase protein, decreases its concentration during infection and inflammation." (PMID 38303719, 2024). "However, compared to the non-infection group and non-low albumin group, the infection group and low albumin group still demonstrated lower levels of Ki-67 and interferon-γ production in T cells." (PMID 38111573, 2023). "To investigate whether IV infection impairs alveolar protein clearance, we examined albumin uptake and megalin expression in MLE-12 cells and alveolar epithelial cells (AEC) from murine precision-cut lung slices (PCLS) and in vivo, under IV infection conditions by flow cytometry and western blot." (PMID 37727782, 2023). "In addition, when low albumin accompanies high CRP, it can be an indicator of infection." (PMID 37308964, 2023). "Second, we could not obtain information about the infection and fluid status of patients, which could affect the serum albumin level and total lymphocyte count." (PMID 36678182, 2023). "Fifth, active infection may have a potential influence on PNI, albumin and lymphocyte levels." (PMID 37567925, 2023). "However, there is limited evidence of the administration of albumin in the prevention of HRS in non-SBP infections." (PMID 37680416, 2023).
infection (continued). "Human albumin was detected in all samples and no statistically significant variance in albumin intensity could be found in these post infection convalescent plasma samples." (PMID 36292212, 2022). "More research is needed in this area because it is still not clear whether the infection worsened due to the patient’s long-term hypoproteinemia or whether the serum albumin decreased sharply when dealing with the infection." (PMID 36472981, 2022). "In addition, the initial serum albumin levels, infections, the total amount, or the initial timing of infusion did not affect the conclusion." (PMID 35721190, 2022). "In addition, since albumin is a negative acute phase protein, its concentration can easily alter in response to infection or inflammation." (PMID 35800664, 2022). "Finally, CRP and albumin, and thereby GPS, could have beeninfluenced by other factors, ie, infection, inflammation, comorbidity, nutrition,and medication (eg, corticosteroids), but our study was not designed to collect suchdata." (PMID 35342321, 2022). "BAPEN (British Association for Parenteral and Enteral Nutrition) state that a low level of serum albumin may indicate inflammation or infection is present and therefore should not be used to determine nutritional status." (PMID 35640017, 2022). "Albumin is a negative acute phase reactant and is often reduced in severe infection." (PMID 35061794, 2022). "The ALB levels in patients without a definite focus of infection (36.10 (32.00, 37.45) g/L) were significantly higher than those in patients with a definite focus of infection (32.95 (30.53, 37.45) g/L) (p < 0.05)." (PMID 36148158, 2022). "Transcriptional profiling during infection of vaginal epithelial cells revealed that C. glabrata up-regulated the adhesin genes AWP2 and AWP6, as well as several further putative adhesin genes, at the early infection stage in the presence of albumin as compared to infection without it." (PMID 34710198, 2021). "Non-dietary factors that may lower serum albumin levels include inflammation, infection, and advanced age." (PMID 33669914, 2021). "Similarly, neither albumin-augmented damage nor growth was observed when iron was sequestered during infection with the iron chelator BPS." (PMID 34710198, 2021). "Monitoring albumin levels in VVC patients could be of importance to predict the infection outcome, but no study so far measured this parameter." (PMID 34710198, 2021). "Albumin (Alb) as a negative acute-phase protein, is considered a measure of the intensity of the infection-triggered inflammatory response, because inflammatory conditions can decrease Alb levels by altering hepatic-protein metabolism and inducing capillary leakage." (PMID 34137842, 2021). "Protein synthesis can decrease during infection due to the preferential synthesis of specific proteins, and albumin may act as an acute-phase negative protein." (PMID 32695119, 2020). "Albumin level in sera from non-vaccinated sheep also decreased after infection with RVFV." (PMID 32793399, 2020). "The α-, β- and γ-globulins are known to include positive acute phase proteins or immunoglobulins and their concentrations often increase in response to an infection or inflammation, while prealbumin and albumin are negative acute phase proteins as their concentrations often decrease." (PMID 31409365, 2019). "Using a multiplicity of infection (MOI) of 0.1 or 10, the K. kingae strains were incubated with or without purified human neutrophils for 1 h in the presence of 1% normal human serum (NHS) as a source of serum opsonins or 1% human serum albumin (HSA) as a control." (PMID 31239373, 2019). "Therefore, a lack of serum albumin suggests chronic damage to the liver as a result of infection (Mahmoodzadah, Mazani & Rezagholizadeh, 2017)." (PMID 30805250, 2019). "During BTV and FMDV infections, the level of the albumin LALBA (a negative APP) was decreased)." (PMID 30223561, 2018).
infection (continued). "However, albumin did not vary consistently with infection in this study: We observed a decrease only with respect to Hemoproteus burden." (PMID 30271545, 2018). "In this research, we found that 6 × 104 PFU RSV primary infection could result in obvious proteinuria but not reduced levels of serum albumin or extensive effacement of foot process in the glomeruli." (PMID 27747195, 2016). "The fact that ALB tended to have higher expression in infected than uninfected individuals in lung, GI2 and GI4 tissues suggests that ALB may be upregulated in response to AIV infection in ducks." (PMID 26886224, 2016). "However, the bacterial entry into brain, PMN transmigration across the BBB, and BBB permeability indicated by albumin concentration in CSF were all significantly reduced in vimentin knockout and with IbeA deletion (ZD1) as compared to wild-type mice with E44 infection." (PMID 27657497, 2016). "In addition, IL-10 treatment did not alter barrier permeability as determined by serum albumin levels in recovered BAL fluid 24 h after infection with S. pneumoniae." (PMID 25595646, 2015). "It is interesting to note, that indomethacin tends to lower serum albumin, even without infection." (PMID 25001579, 2014). "Few data exist regarding the effect of albumin administration in patients with non-SBP infections." (PMID 24222902, 2013). "Since infection is a potent trigger of inflammation, we hypothesized that CRP levels at discharge would correlate with long-term mortality in septic patients and that the CRP/albumin ratio would be a better marker of prognosis than CRP alone." (PMID 23555017, 2013). "Mean decreasein IgG ranged from 27% to 32% in other studies.Although acute mean reductions of 59.7% in fibrinogen,21.5% in serum protein, 14.7% in serum albumin, and14.2% in platelets were noted, we did not observe any infection,hemorrhagia, or edema in our patients." (PMID 24385721, 2012). "Indeed, except for albumin, no other biochemical marker measured during the operation was predictive of infection in the postoperative period in the light of multivariate analysis." (PMID 17505683, 2007). "NNIS, albumin, CRP and IL-6 may be useful as predictive markers for postoperative infections." (PMID 17505683, 2007). "Finally, albumin can be considered as a help in the enhancement of some endogenous antimicrobial peptides for proper and effective care of some, though not all, human infections." (PMID 41148665, 2025). "The lower levels of serum albumin in our NTM-positive patients may be explained mainly by reduced synthesis, accelerated catabolism, and altered body distribution of albumin resulting from the combined effects of a more severe infection, inflammation, and poor nutritional status." (PMID 39010067, 2024). "However, the use of a single indicator for evaluating diseases using LDH or ALB has limitations, as both are affected by multiple diseases, making the prognosis of SFTS patients difficult, and prone to misdiagnosis or missed diagnosis, especially in the early stages of infection." (PMID 39741938, 2024). "Finally, the serum albumin concentration may be affected by various clinical conditions, such as infection, but we could not obtain information about this." (PMID 37686863, 2023). "About 25% of these patients had inflammation due to an infection, and the increase in albumin concentration over time in these patients may be due to the resolution of inflammation with subsequent increases in albumin concentrations, and rather than nutritional effects." (PMID 37419969, 2023). "However, the albumin, cholesterol, and glucose levels could have been affected by diet, rather than by the infection." (PMID 34696468, 2021). "The more severe PGE2-mediated monocyte dysfunction in patients hospitalised with AD/ACLF compared with OPDs could partly explain the lack of effect of albumin infusions in the prevention of infection in the ATTIRE trial, compared with the reduction in infections in the ANSWER trial." (PMID 34825153, 2021).
infection (continued). "We initially infected mice with swollen R. delemar spores with or without pre-exposure to albumin-bound FFAs and assessed neutrophil responses in BAL fluid at 6 h of infection." (PMID 41279284, 2025). "Regarding pathogen-infection-related differences, both ESR (30 min and 1 h) and globulin values were higher in infected bears than in non-infected bears, whereas albumin and A/G values were higher in non-infected bears." (PMID 38807241, 2024). "Other biochemical parameters, such as alanine aminotransferase (ALT), albumin (ALB), blood urea nitrogen (BUN) and serum creatinine (CREA) did not change significantly during infection." (PMID 37033979, 2023). "The univariate analysis revealed the negative effects of smoking, preoperative albumin level, cachexia, T4 stage, neck dissection, entire resection of the floor of the mouth (FOM), segmental mandibulectomy, and surgical site infection on OCF occurrence." (PMID 35924155, 2022). "Although it does not mediate albumin transcytosis, there is evidence that lung endothelial CD36 is involved in the response to inhaled pollutants or infection." (PMID 34638659, 2021). "Infection experiments with Alb+IFN-β reporter mice (AlbCre+/−Ifnbflox-βluc mice), carrying a functional reporter only in Albumin+ (Alb+) hepatocytes, revealed that hepatocytes did not contribute to the IFN-β induction in the liver between 4 and 96 hpi." (PMID 31249303, 2019). "During the 20 months of dialysis, the patient did not contract any infections, CRP remained at lower levels compared with the conservative phase (CRP 10.4±1.7 versus 17.4±3.9 mg l−1), whereas albumin levels stabilized (3.89±0.12 g d l−1)." (PMID 26926587, 2016). "Is albumin useful in cirrhotic patients with infections, with particular focus on SBP and non-SBP infections?" (PMID 24222902, 2013). "We would recommend three studies of albumin and plasma expanders which are in the context of paracentesis, non-SBP, and SBP infections." (PMID 24222902, 2013). "Both guidelines support the use of albumin in spontaneous bacterial peritonitis but there are currently no guidelines for non-SBP infections." (PMID 24222902, 2013). "Although the addition of albumin did not enhance infectivity in SFM (not shown), the addition of EGF and KGF in SFM dramatically restored infection in dose dependent manners." (PMID 22346752, 2012). "At various times after infection, DEF cells infected with DPV were fixed with 4% paraformaldehyde, treated with 5% bovine serum albumin (BSA) to block nonspecific binding and reacted with the DPV gC antiserum." (PMID 21110887, 2010). "Compare to the blank group (healthy mice without any infection and treatment), the levels of AST, DBIL and ALB were significantly increased in the combination group; and the levels of ALT, AST, DBIL, ALP, and γ-GT were significantly increased in the Ubenimex group and Albendazole group." (PMID 38585297, 2024). "In contrast, BSP levels were not correlated with serum levels of sodium, potassium, albumin, urea, bilirubin, aspartate/ alanine-aminotransferases, cholinesterase, gamma-glutamyltransferase, INR, ammonium and markers of systemic inflammation or infection." (PMID 32302330, 2020). "Moreover, the levels of BAL albumin and LDH in infected infant mice were significantly higher compared to non-infected controls indicating that infection altered the permeability of the bronchoalveolar–capillarity barrier and induced cytotoxicity." (PMID 30395582, 2018). "Eight of them (FN1, ALB, CTSL1, OTFB, LYZ, CATHL1, MMP9, LECT2) did not change their expression at the level of transcription and transcripts of 3 of them (RSFR, LYG2, CSTC) even increased following infection." (PMID 28623956, 2017). "Unlike the expression of uPA transgene under albumin promoter (Alb-uPA) as originally described, MUP-uPA/SCID/Bg mice studied in this report, provide a long window of time (up to 12 months) for hepatocyte engraftment and efficient infection with HBV or HCV." (PMID 26217396, 2015).
infection (continued). "After adjusting for age, DM, albumin levels, gender, and dialysis modality, non-seroconversion following HBV vaccination could independently predict mortality due to infection in ESRD dialysis patients." (PMID 22935561, 2012). "In the present study, we demonstrated that DM, age, low albumin levels, and non-response following HBV vaccination could predict mortality due to infection." (PMID 22935561, 2012). "Serum albumin levels slightly decreased from a pre-LASV challenge mean of 3.0 g/dL to 1.8 g/dL by day 17; however, total protein levels did not substantially fluctuate during the course of infection." (PMID 21548931, 2011). "The patients who did not achieve infection eradication were noted to have a significantly higher preoperative CRP (197.9 ± 120.2 vs. 142.2 ± 98.1 years, p = 0.016) and trend towards a higher ESR (70.5 ± 35.8 vs. 56.0 ± 35.5 years, p = 0.067) but similar albumin levels (p = 0.542)." (PMID 38247607, 2024). "Although our results showed the existence of infection did not affect the prognostic significance of scoring systems, we could not exclude the possibility of other confounding effects that deranged CRP or albumin levels during infection may produce." (PMID 30367618, 2018).